C5AR1 (complement C5a receptor 1)
Diseases named in the same sentence as C5AR1 in open-access papers (continued):
Sharing a sentence is not in itself a finding about the gene and the disease.
endometrial carcinoma (1 paper, 2021). A malignant tumor arising from the epithelium that lines the cavity of the uterine body. "Here, thyroid carcinomas, small-cell lung cancer, gastrointestinal stromal tumours and endometrial carcinomas displayed noticeable C5aR1 expression in a high percentage of samples." (PMID 33606748, 2021). "In addition to confirming published findings, we found noticeable C5aR1 expression in many tumour entities, such as in thyroid carcinomas, small-cell lung cancer, gastrointestinal stromal tumours and endometrial carcinomas, for the first time." (PMID 33606748, 2021). "C5aR1 was also highly expressed in the vast majority of the 32 tumour entities investigated, where a hitherto unappreciated high prevalence of the receptor was detected in thyroid carcinomas, small-cell lung cancer, gastrointestinal stromal tumours, and endometrial carcinomas." (PMID 33606748, 2021).
endometriosis (1 paper, 2025). The growth of functional endometrial tissue in anatomic sites outside the uterine body. "Activation of the complement cascade in endometriosis generates powerful pro-inflammatory mediators—anaphylatoxins C3a and C5a—which bind to specific receptors (C3aR and C5aR1/CD88) on immune cells, triggering intense inflammatory reactions." (PMID 41488658, 2025).
Erythema (1 paper, 2019). Redness of the skin, caused by hyperemia of the capillaries in the lower layers of the skin. "Topical application of IMQ on the shaved back of wild-type C5aR1+/+ mice for six consecutive days induced psoriatic lesions, including erythema, scales, and crust formation, as previously reported." (PMID 31447855, 2019).
esophageal carcinoma (1 paper, 2025). A primary or metastatic malignant neoplasm involving the esophagus. "Elevated expression of C5AR1 correlated with a poor prognosis, resulting in shorter overall survival in esophageal carcinoma and lung SCC." (PMID 40056975, 2025).
Fabry disease (1 paper, 2024). Fabry disease (FD) is a progressive, inherited, multisystemic lysosomal storage disease characterized by specific neurological, cutaneous, renal, cardiovascular, cochleo-vestibular and cerebrovascular manifestations. "The mechanisms by which the C3a–C3aR and C5a–C5aR1 axes drive excessive leukocyte recruitment in Fabry disease remain critical areas of research." (PMID 39596318, 2024). "Together, these findings implicate the C3a–C3aR and C5a–C5aR1 pathways as key modulators in Fabry disease, driving the upregulation of MHC II on circulating monocytes." (PMID 39596318, 2024). "Targeting the C3a–C3aR and C5a–C5aR1 pathways and their influence on adhesion molecule-mediated immune cell infiltration holds significant promise for mitigating inflammation and potentially halting or slowing the progression of organ damage in Fabry disease." (PMID 39596318, 2024). "Targeting complement components C3a, C5a, or their respective receptors, C3aR (C3a receptor) and C5aR1 (C5a receptor 1), could potentially reduce inflammation, mitigate tissue damage, and improve clinical outcomes for individuals with Fabry disease." (PMID 39596318, 2024). "In the context of Fabry disease, C3a–C3aR- and C5a–C5aR1-mediated upregulation of P selectin could enhance leukocyte adhesion and rolling on the endothelium, leading to an increased tissue recruitment of leukocytes." (PMID 39596318, 2024).
gastric tumor (1 paper, 2024). "Analysis of C5aR1 mRNA levels in gastric tumor tissues, sourced from the bioinformatics TCGA-STAD cohort and the Genotype-Tissue Expression (GTEx) project, revealed a significant upregulation compared to normal gastric tissues." (PMID 39850877, 2024).
Gaucher disease (1 paper, 2024). Gaucher disease (GD) is a lysosomal storage disorder encompassing three main forms (types 1, 2 and 3), a fetal form and a variant with cardiac involvement (Gaucher disease - ophthalmoplegia - cardiovascular calcification or Gaucher-like disease). "This recruitment was markedly diminished in both the C5aR1-deficient Gba1 9V/- and the C5aR1-deficient CBE-mediated glucocerebrosidase-targeted mouse models of Gaucher disease, emphasizing the role of C5aR1 in this process." (PMID 39596318, 2024).
HCMV infection (1 paper, 2017). "Network analysis of the differentially expressed genes in cord DCs, revealed among the downregulated genes after 16 h of HCMV infection several GPCRs with pro-inflammatory response function (ADORA3, ARRB1, C5AR1, CXCR4, GPR34, GPR183, GRK3, and RGS18)." (PMID 28993767, 2017). "In addition to these, HCMV infection of cord DCs resulted in a suppression of several other GPCRs [including GPR68, GPR183 (EBI2), and GPR146] that, together with C5AR1, CXCR4, and RGS18, have been shown to be highly enriched in unstimulated macrophages and dendritic cells." (PMID 28993767, 2017).
head and neck squamous cell carcinoma (1 paper, 2023). A squamous cell carcinoma that arises from any of the following anatomic sites: lip and oral cavity, nasal cavity, paranasal sinuses, pharynx, larynx, and salivary glands. "Additionally, elevated C5aR1 expression has been linked to poor survival in patients with head and neck squamous cell carcinomas." (PMID 37760630, 2023).
Hepatic steatosis (1 paper, 2023). Steatosis is a term used to denote lipid accumulation within hepatocytes. "Overall, our study demonstrates that C5aR1 deficiency has reduced effect on hepatic steatosis, inflammation and fibrosis in NASH mice." (PMID 37227481, 2023). "C5aR1 deletion or blockade of C5aR1 with antagonist alleviates hepatic steatosis, inflammation, and fibrosis in NASH mice." (PMID 37227481, 2023). "Blockade of the C5a–C5aR1 axis reduces hepatic steatosis, inflammation, and fibrosis in NASH mice." (PMID 37227481, 2023).
hookworm infection (1 paper, 2024). "In conclusion, our findings highlight the impact of C5aR1 signaling in neutrophils during hookworm infection uncovering an unexpected downside of complement activation in parasitic infection." (PMID 39628481, 2024). "Our data implicate a role for dysregulated neutrophil responses in the protection of C5aR1-/- mice during pulmonary hookworm infection." (PMID 39628481, 2024). "Surprisingly, C5aR1 presence directly contributed to the pathogenicity of hookworm infection." (PMID 39628481, 2024).
intracerebral hemorrhage (1 paper, 2019). A cerebrovascular disorder characterized by bleeding into one or both cerebral hemispheres including the basal ganglia and the cerebral cortex. "C5aR1 antagonist treatment could block neutrophil extravasation into the brain parenchyma after traumatic brain injury or intracerebral hemorrhage, contributing to reduced tissue damage and improved spatial memory after brain injury." (PMID 31011487, 2019).
intrauterine growth restriction (1 paper, 2021). "Here, the C5a –C5aR1 axis has been related to different pathologies, such as placental dysfunction, pre-eclampsia, intrauterine growth restriction, and spontaneous abortion." (PMID 33606748, 2021).
kidney (1 paper, 2026). "In recent years, complement 5 (C5) and its anaphylatoxin receptor C5aR1 have been implicated in driving kidney IRI and loss of function." (PMID 42210713, 2026).
kidney injuries (1 paper, 2025). "C5a, one of the most potent inflammatory mediators, was activated in DN and subsequently bound to C5aR1 to promote the recruitment of macrophages and the production of inflammatory cytokines and chemokines, contributing to further kidney injuries." (PMID 40072066, 2025).
leukocytosis (1 paper, 2022). "C5aR1 signaling in mice subjected to systemic envenomation was also responsible for leukocytosis, neutrophilia, monocytosis and acute lung injury, as demonstrated by the use of PMX205 in these assays." (PMID 35720304, 2022).
lysosomal storage disorder (1 paper, 2024). "In Gaucher disease, a lysosomal storage disorder linked to malignant cancers, the accumulation of glucosylceramide and inflammatory response is regulated by the classical pathway-dependent complement activation through C5a–C5aR1 signaling." (PMID 38894892, 2024).
multiple sclerosis (1 paper, 2023). A progressive autoimmune disorder affecting the central nervous system resulting in demyelination. "C3aR1 and C5aR1 might be involved in local tissue repair similar to their upregulation in multiple sclerosis for demyelination and remyelination." (PMID 37207197, 2023).
muscular dystrophies (1 paper, 2022). "The relationship between C3aR1 and C5aR1 and vessel remains obscure and is not yet reported in muscular dystrophies." (PMID 36402750, 2022).
myocarditis (1 paper, 2021). Myocarditis is a condition that is characterized by inflammation of the heart muscle (myocardium). "In contrast, the plastic caging significantly increased the expression of CD11b/CR3 (p = 0.002), C4b (p = 0.002), and the mast cell anaphylatoxin complement receptor C5aR1 (p = 0.006) in males during acute myocarditis compared to glass caging." (PMID 34445539, 2021).
nasal polyp (1 paper, 2020). "Our data of higher gene expression levels of anaphylatoxin receptors C3AR, C5AR1, and C5L2 in CRSwNP tissues, especially for nasal polyp tissues, compared to healthy controls is consistent with the higher load of immune cells expressing these receptors in the chronically inflamed surroundings." (PMID 32724828, 2020).
nerve sheath tumors (1 paper, 2024). "In spite of C5aR1 expression, deletion of C5aR1 has no major impact on any major immune subset in these nerve sheath tumors." (PMID 38458648, 2024).
neurofibroma (1 paper, 2024). An intraneural or extraneural neoplasm arising from nerve tissues and neural sheaths. "Immunohistochemical staining of C5aR1/CD88 in human samples increased expression in neurofibroma versus nerve." (PMID 38458648, 2024). "To define neurofibroma cells expressing C5aR1/CD88, we turned to a mouse model." (PMID 38458648, 2024).
postmenopausal osteoporosis (1 paper, 2022). Metabolic disorder associated with fractures of the femoral neck, vertebrae, and distal forearm. "The aim of the present study was to elucidate the cell-specific role of the C5a/C5aR1 axis in the regulation of physiological bone turnover as well as in the pathophysiology of postmenopausal osteoporosis." (PMID 36246887, 2022). "However, in ovariectomized mice, a common model for postmenopausal osteoporosis, C5aR1 on osteoblasts induces osteoclast activity by increasing the RANKL release." (PMID 36246887, 2022). "Therefore, our results implicate C5aR1 on osteoblasts as a potential target for treating postmenopausal osteoporosis." (PMID 36246887, 2022). "Therefore, our results implicate C5aR1 on osteoblasts as a potential target for the treatment of postmenopausal osteoporosis." (PMID 36246887, 2022). "However, C5aR1 on osteoblasts may exert crucial functions in bone resorption when the system is challenged, because C5aR1Runx2-Cre mice were completely protected from bone loss induced by OVX, a murine model for postmenopausal osteoporosis." (PMID 36246887, 2022). "However, it remains unclear whether the C5a/C5aR1 axis specifically in bone cells plays a role in the development of postmenopausal osteoporosis, as no preclinical and clinical data are available so far." (PMID 36246887, 2022).
Pulmonary hemorrhage (1 paper, 2024). Pulmonary hemorrhage is a bleeding within the lungs. "On the other hand, the disruption of C5aR2 signaling alone or in combination with C5aR1 did not significantly alter pulmonary hemorrhage." (PMID 39628481, 2024).
recessive dystrophic epidermolysis bullosa (1 paper, 2025). "Increased expression of C5aR1 was observed on the surface of tumor cells and fibroblasts in invasive cSCCs and recessive dystrophic epidermolysis bullosa–associated cSCCs compared with cSCC in situ, actinic keratoses, seborrheic keratoses, and normal skin." (PMID 40056975, 2025).
rectal adenocarcinoma (1 paper, 2023). "Analysis of C5aR1 expression in rectal adenocarcinoma biopsies also points to a potential “Goldilocks” effect to C5aR1 expression." (PMID 37824211, 2023). "Furthermore, in previously analyzed RNA-Seq of longitudinal biopsies from patients with rectal adenocarcinoma, we noted that C5aR1 expression was significantly increased following treatment." (PMID 37824211, 2023).
rectal cancer (1 paper, 2023). A primary or metastatic malignant neoplasm that affects the rectum. "Interestingly, in patients with rectal cancer, we found that those classified as CMS4 have the highest levels of C5aR1 expression compared with the other subtypes." (PMID 37824211, 2023).
rectal tumor (1 paper, 2023). "Analysis of pretreatment rectal tumor biopsies identified that those classified as CMS4 had the highest RNA levels of C5aR1 compared with the other subtypes." (PMID 37824211, 2023).
retinal detachment (1 paper, 2023). An eye emergency condition which may lead to blindness if left untreated. "Our results showed that approximately 95.1% of CD45mid CD11b+ P2ry12+ retinal resident microglia were positive for C5aR1 expression and that 100% of resident microglia expressed C5aR1 in retinal detachment." (PMID 37443787, 2023).
scrapie (1 paper, 2018). A fatal disease of the nervous system in sheep and goats, characterized by pruritus, debility, and locomotor incoordination. "To assess the influence of these individual innate immune receptors on CNS prion pathogenesis, we used ic inoculation of 22L scrapie in mice deficient in TLR2 (Tlr2-/-), C3aR1 (C3ar1-/-), or C5aR1 (C5ar1-/-)." (PMID 30596651, 2018).
tularemia (1 paper, 2025). Tularemia is an infection caused by the bacterium Francisella tularensis. "We showed for the first time that mice deficient in C3aR1 and CR2, but not C3 or C5aR1, were more susceptible to tularemia." (PMID 41406154, 2025).
uremia (1 paper, 2023). A clinical syndrome associated with the retention of renal waste products or uremic toxins in the blood. "The current study systematically identified three candidate hub genes (FGR, LCP1, and C5AR1) and established a nomogram to assist in diagnosing USCP with uremia using various bioinformatic analyses and machine learning algorithms." (PMID 36823662, 2023). "Our study systematically identified three candidate hub genes (FGR, LCP1, and C5AR1) and established a nomogram to assist in the diagnosis of USCP with uremia using various bioinformatic analyses and machine learning algorithms." (PMID 36823662, 2023).
tumor (140 papers, 2011 to 2026). "Deficiency in C5aR1 has been shown to reprogram macrophages from a pro-tumor state to an anti-tumor state, resulting in increased immune responses and stimulatory pathways." (PMID 41373839, 2025). "In future research, it will be critical to investigate the downstream signalling pathways involved in C5a-C5aR1 interactions to clarify the mechanisms associated with tumour growth in the immune TME of PDAC." (PMID 41044172, 2025). "Increased expression of C5aR1 on the tumor cell surface and in fibroblasts was associated with metastatic risk and poor disease-specific survival of patients with primary cSCC." (PMID 40056975, 2025). "We recently reported that complement component C5a receptor 1 (C5aR1/CD88) can cause treatment resistance following radio- and chemotherapy in tumours with an immunosuppressive TME." (PMID 40695778, 2025). "This study reveals the mechanism by which the C5a-C5aR1 pathway regulates tumor-associated macrophage (TAM) anti-tumor immune responses and highlights the potential of targeting C5aR1 for clinical applications." (PMID 41373839, 2025). "Markiewski demonstrated that the C5a/C5aR1 axis is associated with the activation, recruitment, and distribution of MDSCs in tumours." (PMID 41044172, 2025). "We found that the reduced tumor growth by C5aR1 deficiency was abolished in the administration of the ABX cocktail." (PMID 38331868, 2024). "Our data demonstrated that C5aR1 deficiency or C5aR1 inhibition re-programmed TAMs to a tumor-inhibiting phenotype." (PMID 38331868, 2024). "This is consistent with C5ar1 inhibiting expression of genes associated with inflammatory and anti-tumor activities." (PMID 38802355, 2024). "C5aR1 has previously been implicated in mediating pro-tumor macrophage polarization and in creating a pro-tumor microenvironment." (PMID 38802355, 2024). "Targeting C5aR1 modulates the function of infiltrated immune cells including tumor-associated macrophages (TAMs)." (PMID 38331868, 2024). "Based on our results using animals with loss of C5aR1, we anticipate that this combination will have significant local tumor effects with minimal systemic toxicity." (PMID 38458648, 2024). "In contrast, blockade of TLR5 attenuated C5aR1 inhibition-regulated tumor suppression in association with a decrease in CD86 expression and glycolysis in macrophages." (PMID 38331868, 2024). "Blockade of the complement receptor C5AR1 enables tumor-associated macrophages to be reprogrammed and reinvigorated CD8+ T-cell-mediated antitumor immunity, thereby synergizing with anti-PD-1 therapy for GC tumor eradication." (PMID 38425243, 2024). "This is consistent with our trajectory analysis that implicates C5aR1 in the transition whereby macrophages express genes associated with pro-tumor functions." (PMID 38802355, 2024). "Here, in preclinical models of BRCA1/2 wild type and homologous recombination competent BC, the authors show that C5aR1-positive tumor associated macrophages are associated with PARPi-resistance, suggesting targeting C5aR1 as a therapeutic option." (PMID 38802355, 2024). "Previous studies have shown that C5aR1 can cause tumor-related immunity by inducing the production of bioactive molecules in the tumor microenvironment." (PMID 39368999, 2024). "Complement-associated proteins can act as antagonists and increase tumour cell proliferation, migration, and invasion and induce angiogenesis, as observed with antagonists of C5aR1 and C3aR." (PMID 37091785, 2023). "A multi-omics analysis has found an association between C3/C5/C3AR1/C5AR1 and tumor immune evasion and therapy response in several types of cancer." (PMID 37628784, 2023). "The C5a/C5aR1 activation pathway has been implicated in various inflammatory processes, the pathogenesis of immune diseases, and tumor growth." (PMID 36508191, 2023).